NANOGP1 (Nanog homeobox pseudogene 1)
Description:
Probable transcriptional regulator.
Synonyms: NANOG2
Gene: Transcribed unprocessed pseudogene on chromosome 12 (7,892,576 to 7,898,903, forward strand). Ensembl gene ENSG00000176654.
Subcellular location: Nucleus
Diseases named in the same sentence as NANOGP1 in open-access papers:
NANOGP1 is named in the same sentence as 1 disease in open-access papers, as found by Europe PMC text mining. Sharing a sentence is not in itself a finding about the gene and the disease.
NANOGP1 shares sentences with these, for which no sentence is quoted: breast tumors (1 paper).